FAM90A5 (family with sequence similarity 90 member A5)
Synonyms: FAM90A5P
Tractability: No criterion of Open Targets' tractability assessment is met for any kind of drug.
Gene: Protein-coding gene on chromosome 8 (7,287,392 to 7,290,402, forward strand). Ensembl gene ENSG00000215373.
Subcellular location (Human Protein Atlas): Nucleoplasm; Nucleoli
Homologues: Orthologues: mouse Fam90a1b (28% identical), mouse Fam90a1a (27% identical), rat Fam90a1l1 (26% identical). Paralogues in human: FAM90A15 (99% identical), FAM90A13 (99% identical), FAM90A14 (99% identical), FAM90A3 (99% identical), FAM90A11 (98% identical), FAM90A23 (98% identical), FAM90A16 (98% identical), FAM90A17 (98% identical), FAM90A24 (98% identical), FAM90A9 (98% identical), FAM90A18 (97% identical), FAM90A19 (97% identical), and 9 more.